VLDLR (very low density lipoprotein receptor)
Description:
Multifunctional cell surface receptor that binds VLDL and transports it into cells by endocytosis and therefore plays an important role in energy metabolism. Also binds to a wide range of other molecules including Reelin/RELN or apolipoprotein E/APOE-containing ligands as well as clusterin/CLU. In the off-state of the pathway, forms homooligomers or heterooligomers with LRP8. Upon binding to ligands, homooligomers are rearranged to higher order receptor clusters that transmit the extracellular RELN signal to intracellular signaling processes by binding to DAB1. This interaction results in phosphorylation of DAB1 leading to the ultimate cell responses required for the correct positioning of newly generated neurons. Later, mediates a stop signal for migrating neurons, preventing them from entering the marginal zone (By similarity). (Microbial infection) Acts as a receptor for Semliki Forest virus. (Microbial infection) Functions as a receptor for yellow fever virus.
Synonyms: VLDL-R; CARMQ1; CHRMQ1; VLDLRCH; CAMRQ1
Tractability: Antibody: UniProt places it where antibodies can reach, with high confidence; its Gene Ontology location is reachable by antibodies, with high confidence; UniProt predicts a signal peptide or a membrane-spanning region. PROTAC: UniProt records ubiquitination sites on it; ubiquitination databases record sites on it; its protein half-life has been measured.
Gene: Protein-coding gene on chromosome 9 (2,621,182 to 2,660,056, forward strand). Ensembl gene ENSG00000147852.
Subcellular location: Cell membrane; Membrane, clathrin-coated pit
Subcellular location (Human Protein Atlas): Vesicles; Centriolar satellite; Cytokinetic bridge
Pathways (Reactome):
Transport of small molecules: VLDL clearance; VLDLR internalisation and degradation
Developmental Biology: Reelin signalling pathway
Gene Ontology:
Molecular function: apolipoprotein binding; calcium-dependent protein binding; cargo receptor activity; protein binding; very-low-density lipoprotein particle binding; very-low-density lipoprotein particle receptor activity; virus receptor activity; low-density lipoprotein particle receptor activity; reelin receptor activity; calcium ion binding
Biological process: glycoprotein transport; receptor-mediated endocytosis; very-low-density lipoprotein particle clearance; memory; nervous system development; positive regulation of dendrite development; reelin-mediated signaling pathway; signal transduction; endocytosis; symbiont entry into host cell
Cellular component: membrane; plasma membrane; receptor complex; lysosomal membrane; clathrin-coated pit
Genetic constraint (gnomAD): Loss-of-function variants: 78 observed, 113.72 expected, observed/expected ratio (o/e) 0.69, 90% interval 0.57 to 0.83. The upper end of that interval is the gene's LOEUF score, 0.83, which puts it in group 3 of 6, group 1 being the genes least tolerant of losing a copy. Missense variants: 1,236 observed, 1,143.6 expected, observed/expected ratio (o/e) 1.08, 90% interval 1.03 to 1.13. Synonymous variants: 436 observed, 400.92 expected, observed/expected ratio (o/e) 1.09, 90% interval 1 to 1.18.
Gene-disease validity (ClinGen):
ClinGen rates the evidence that VLDLR causes each of these diseases.
cerebellar ataxia, intellectual disability, and dysequilibrium syndrome 1 (autosomal recessive): Definitive.
Homologues: Orthologues: macaque VLDLR (99% identical), chimpanzee VLDLR (97% identical), rabbit VLDLR (97% identical), mouse Vldlr (96% identical), rat Vldlr (96% identical), dog VLDLR (95% identical), pig VLDLR (95% identical), guinea pig VLDLR (93% identical), tropical clawed frog vldlr (75% identical), zebrafish vldlr (69% identical), Drosophila melanogaster arr (19% identical). Paralogues in human: LRP8 (48% identical), LRP1 (36% identical), LRP1B (35% identical), LRP2 (35% identical), LRP4 (31% identical), LRP5 (23% identical), LRP6 (22% identical), NID1 (21% identical), EGF (20% identical), NID2 (19% identical), LRP12 (16% identical), and 2 more.
Diseases named in the same sentence as VLDLR in open-access papers:
VLDLR is named in the same sentence as 107 diseases in open-access papers, as found by Europe PMC text mining. Sharing a sentence is not in itself a finding about the gene and the disease. The quoted sentences say what the papers report.
Hepatic steatosis (20 papers, 2013 to 2025). Steatosis is a term used to denote lipid accumulation within hepatocytes. "Recently, the very low-density lipoprotein receptor (VLDLR) has also been implicated in the development of hepatic steatosis." (PMID 32912335, 2020). "Tm-induced ERS causes hepatic steatosis via the upregulation of a very low-density lipoprotein receptor (VLDLR) and consequently increases lipoprotein delivery to the liver." (PMID 31500117, 2019). "Moreover, a previous study has reported increased hepatic lipid accumulation induced by VLDLR overexpression, while VLDLR‐deficient mice were protected from hepatic steatosis induced by HFD feeding." (PMID 31595673, 2019). "Since hepatic VLDLR levels are elevated in response to ER stress and as they contribute to ER stress-dependent hepatic steatosis, we next evaluated whether SIRT1 activation attenuated VLDLR upregulation and the hepatic steatosis caused by the ER stressor tunicamycin." (PMID 38807218, 2024). "Endoplasmic reticulum (ER) stress-mediated increases in the hepatic levels of the very low-density lipoprotein (VLDL) receptor (VLDLR) promote hepatic steatosis by increasing the delivery of triglyceride-rich lipoproteins to the liver." (PMID 38807218, 2024). "First, we examined the protein levels of VLDLR in the livers of rats supplemented with fructose, a well-known inducer of fatty liver." (PMID 38807218, 2024). "In fact, tunicamycin leads to hepatic steatosis by several mechanisms, including an increase in the hepatic levels of VLDLR and the subsequent uptake of VLDL particles." (PMID 38807218, 2024). "Inhibiting the upregulation of VLDLR can protect mice from hepatic steatosis induced by a high-fat diet." (PMID 37078747, 2023). "Fibroblast growth factor 21 also promotes endoplasmic reticulum stress-related VLDLR overexpression in hepatic steatosis." (PMID 35457118, 2022). "Recent data has revealed that the activated PERK–eIF2α–ATF4 pathway during ER stress induces hepatic steatosis via increase VLDLR by enhancing intracellular TG accumulation with VLDL uptake." (PMID 31632274, 2019). "Previous study has demonstrated that inhibition of VLDLR upregulation can protect mice against hepatic steatosis induced by HFD feeding." (PMID 31632274, 2019). "Accordingly, chronic alcohol intake increased CD36 and very low density lipoprotein receptor (VLDLR) expression in the liver, whereas knock-out of these receptors protected mice from the development of alcohol-induced fatty liver." (PMID 28212318, 2017). "In conclusion, MEAO attenuates ER stress and prevents hepatic steatosis pathogenesis via inhibition of expression of the hepatic lipogenic genes and VLDLR, and enhancement of ApoB secretion." (PMID 26540043, 2015). "Together, these results suggest that MEAO attenuated ER stress and ameliorated hepatic steatosis via the downregulation of VLDLR expression, and the improvement of ApoB secretion under conditions of suppressed lipogenesis." (PMID 26540043, 2015). "In conclusion, MEAO efficiently attenuated ER stress and prevented the development of hepatic steatosis through inhibition of the expression of hepatic lipogenic genes and of VLDLR, and enhancement of ApoB secretion." (PMID 26540043, 2015). "However, the discovery that ER stress stimulates hepatic steatosis by increasing the expression of hepatic VLDLR demonstrates that increased lipoprotein delivery to the liver is a new determinant in hepatic steatosis." (PMID 38807218, 2024). "Interestingly, it has been reported that the endoplasmic reticulum (ER) stress-mediated increase in the levels of the VLDL receptor (VLDLR) results in remarkable hepatic steatosis via enhanced triglyceride-rich lipoprotein delivery to the liver." (PMID 38807218, 2024). "Interestingly, even the induction of a mild liver steatosis with a low percentage of fructose for a relatively short period of time resulted in an increase in the protein levels of VLDLR, while the protein levels of SIRT1 were reduced." (PMID 38807218, 2024).
Hepatic steatosis (continued). "ER stress stimulates liver steatosis by increasing the expression of VLDLR." (PMID 37078747, 2023). "VLDLR plays an important role in hepatic steatosis and is governed by LNC_000027 and LNC_000426." (PMID 34368149, 2021). "By contrast, the hepatic protein levels of VLDLR, which were reported to increase in animal models and humans with hepatic steatosis, were significantly reduced by GCE, compared to the CAF group, although they were not significantly modified by the HF-HFr diet." (PMID 33113993, 2020). "In conclusion, this study provides compelling evidence to support that PA is effective in ameliorating hepatic steatosis caused by HFD through suppressing ER stress and regulating VLDL uptake, assembly, and secretion, which is associated with the regulation of VLDLR, apoB100, and MTP expression." (PMID 31632274, 2019). "As this inhibition of triglyceride transport is rescued in leptin-deficient mice, regulating VLDL metabolism by hepatic VLDLR, LPL, and leptin may represent a new therapeutic strategy for preventing diet-induced liver steatosis." (PMID 31815184, 2019). "ER stress has been shown to increase VLDLR expression and inhibit ApoB secretion, which might be a primary mechanism of tunicamycin-induced hepatic steatosis under conditions of suppressed lipogenesis." (PMID 26540043, 2015). "Furthermore, FGF21 may protect against hepatic steatosis by attenuating ER stress-induced VLDL receptor (VLDLR) upregulation and suppressing the maturation level of SREBP1 protein induced by ER stress." (PMID 36618930, 2022). "Hepatic PPARβ/δ activation suppresses SREBP-1c,461 regulates the lipoprotein-related genes (VLDLR, ApoA5, ApoA4, and ApoC1), and enhances FAO, thereby reducing triglyceride and hepatic steatosis." (PMID 41438090, 2025). "The low-carbohydrate ketogenic diet induces hepatic VLDLR gene expression and promotes triglyceride clearance from VLDL in the liver, consequently protecting against liver steatosis progression." (PMID 35565871, 2022). "LCKD-induced VLDLR expression promotes triglyceride clearance from VLDL in the liver and the progression of liver steatosis." (PMID 31815184, 2019). "Here, we show that the presence of hepatic steatosis in a model of MASLD induced by fructose-drinking water was accompanied by a reduction in hepatic SIRT1 protein levels and an upregulation of VLDLR levels, suggesting a potential relationship between these two proteins." (PMID 38807218, 2024). "Upregulation of VLDLR expression in the liver, which occurs after prolonged exposure to endoplasmic reticulum stress, occurs via activation of transcription factor 4 (ATF4) signaling and induces hepatic steatosis." (PMID 35457118, 2022). "The induction of hepatic VLDLR expression by fenofibrate or over-expression of VLDLR decreases triglyceride-rich VLDL levels via triglyceride clearance by the liver, which can promote the development of liver steatosis." (PMID 31815184, 2019). "Recently, it was reported that tunicamycin-induced ER stress increased the expression of very low-density lipoprotein receptor (VLDLR), which could contribute to hepatic steatosis." (PMID 26540043, 2015).
cerebellar ataxia (14 papers, 2012 to 2024). A neurological syndrome characterized by clumsy and uncoordinated movement of the limbs, trunk, and cranial muscles. "Similar to our dogs peripheral ataxia of the limbs, loss of smooth pursuit eye movements and epileptic seizures occur in some humans with VLDLR-associated cerebellar hypoplasia." (PMID 25668516, 2015). "This study gave rise to the term “VLDLR-associated cerebellar ataxia”, which is a clinically and molecularly well-defined subgroup of the so called dysequilibrium syndrome." (PMID 25668033, 2015). "VLDLR associated forms of dysequilibrium syndrome were recently re-named into “cerebellar ataxia, mental retardation, and dysequilibrium syndrome 1” (CAMRQ1, OMIM #224050)." (PMID 25668033, 2015). "Variants in the VLDLR gene have been shown to cause congenital cerebellar ataxia and mental retardation in human patients and Vldlr knockout mice also display an ataxia phenotype." (PMID 25668033, 2015). "Interestingly, VLDLR mutations have been associated with recessive cerebellar hypoplasia characterized by cerebellar ataxia, mental retardation, strabismus, dysarthria and seizures." (PMID 33671313, 2021). "From the figures, it can be seen that differences related to ataxia are significant, and genes with strong correlations are VLDLR, ALDH5A1, and CACNA1C, and strong correlations means these correlations between gene variants and ataxia (or phenotype)." (PMID 31291898, 2019). "Homozygous inactivation of the VLDLR gene in humans results in cerebellar hypoplasia with mild cerebral gyral simplification, which leads to mental retardation, dysarthric speech and cerebellar ataxia, and sometimes quadrupedal gait." (PMID 30304853, 2018). "For example, previous studies have shown that misregulation of VLDLR leads to many neurodevelopmental disorders, including cerebellar ataxia, mental retardation and disequilibrium syndrome (CAMRQ1) and cerebellar hypoplasia." (PMID 30333515, 2018). "In conclusion we identified a single base deletion in the VLDLR gene in dogs with cerebellar hypoplasia and ataxia, a phenotype termed Dandy-Walker-like malformation (DWLM)." (PMID 25668033, 2015). "The condition has been classified into cerebellar ataxia, mental retardation and disequilibrium syndrome types 1 (CAMRQ1), 2 (CAMRQ2) and 3 (CAMRQ3) and attributed to mutations in VLDLR, CA8 and WDR81 genes, respectively." (PMID 22973972, 2012). "Biallelic pathogenic variants in the VLDLR gene (MIM 192977) cause VLDLR cerebellar hypoplasia, which is a subtype of dysequilibrium syndrome that combines non-progressive cerebellar ataxia with moderate to profound intellectual disability (ID) (MIM 224050)." (PMID 39085459, 2024). "The defects in PC migration and dendrite maturation, as well as the ataxia and tremor present in PlaaG23V/G23V mice may, therefore, result from the accumulation of dysfunctional VLDLR due to disrupted post-endocytic trafficking to the lysosome." (PMID 28413018, 2017). "Both genes have been implicated in rare Mendelian disorders: VLDLR (very low-density lipoprotein receptor) – cerebellar ataxia, mental retardation, and disequilibrium syndrome 1, CAMRQ1, MIM#224050 and KCNV2 (voltage-gated potassium channel subunit Kv8.2) – retinal cone dystrophy, RCD3B, MIM#610356." (PMID 24498604, 2013). "The life span of VLDLR−/− mice is normal and they do not develop recognizable ataxia." (PMID 30304853, 2018).
Obesity (14 papers, 2010 to 2023). Accumulation of substantial excess body fat. "There is convincing evidence that VLDLR is associated with obesity as demonstrated in humans and animal models." (PMID 34165214, 2021). "Interestingly, a third group of genes (CPE, NPY5R, DRD3, TAS2R38, SLC18A1, G6PC3, NPY1R, and VLDLR) was highly associated with both neurological and obesity concepts." (PMID 23544116, 2013). "Studies with VLDLR knock-out mice have linked VLDLR with obesity." (PMID 21966368, 2011). "Hepatic VLDLR expression, which is maintained at the baseline, is significantly upregulated in obesity." (PMID 35700043, 2022). "This study investigated that NK suppresses obesity via the inhibition of oxidative stress‐mediated adipogenesis and the VLDLR signalling pathway." (PMID 34165214, 2021). "Ablation of IDOL also prevents diet-induced obesity through controlling neuronal very low-density lipoprotein receptor, another IDOL target protein." (PMID 33154164, 2021). "NK administration also alleviated HFD‐induced obesity in the animal model via the inhibition of oxidative stress‐mediated adipogenesis and the VLDLR signalling pathway." (PMID 34165214, 2021). "On the contrary, PCSK9 also influences the expression of receptors and molecules other than VLDLR to promote obesity." (PMID 34356856, 2021). "Very low‐density lipoprotein (VLDL)‐VLDLR signalling in ATMs exacerbates adipose tissue inflammation in obesity, indicative of the role of VLDLR in adipose tissue inflammation and adipocyte‐macrophage interactions." (PMID 34165214, 2021). "The VLDLR, IL33 and PTPRD genes were identified as the most interesting genes for obesity-susceptibility within 9p24." (PMID 29441128, 2018). "Collectively, our data suggest that regulation of macrophage VLDLR would be one of potential therapeutic targets in obesity-induced metabolic disorders." (PMID 29057873, 2017). "Here, the authors show that VLDLR, expressed on adipose tissue macrophages, is upregulated in obesity and promotes adipose tissue inflammation by upregulating ceramide production and facilitating M1-like macrophage polarization." (PMID 29057873, 2017). "Here we have shown that elevated VLDLR in ATMs would be a key factor to provoking adipose tissue inflammation and insulin resistance in obesity." (PMID 29057873, 2017). "Nonetheless, our study represents a first approach in the study of VLDLR in human adipose tissue and further studies will be necessary to understand the relationship between VLDLR in human adipose tissue, obesity and insulin resistance." (PMID 21966368, 2011). "In addition, NK administration inhibited adipogenic differentiation and obesity‐induced inflammation and oxidative stress via the suppression of the VLDLR and MEK/ERK1/2 pathways." (PMID 34165214, 2021). "Given that the balance shifting between M1- and M2-like macrophages is critical for the progression of inflammatory responses in obese adipose tissue, it is plausible that macrophage VLDLR elevation in obesity confers systemic insulin resistance through adipose tissue inflammation." (PMID 29057873, 2017). "Moreover, decreased pro-inflammatory signaling in VLDLR-ablated macrophages could prevent systemic insulin resistance in obesity." (PMID 29057873, 2017). "Altogether, our data suggest that upregulated macrophage VLDLR could provoke insulin resistance by enhancing pro-inflammatory signaling pathways, accompanied with altered lipid profiles under lipid-rich conditions in obesity." (PMID 29057873, 2017). "However, it is largely unknown whether macrophage VLDLR might be crucial for obesity-induced insulin resistance through adipose tissue inflammation." (PMID 29057873, 2017). "Validating the hypothesis that PCSK9 provides a defence mechanism against obesity, studies showed that visceral adipose tissue content increases in PCSK9 knockout mice due to increased expression of VLDLR." (PMID 34356856, 2021).
Obesity (continued). "It has been also noted that macrophage VLDLR‐mediated VLDL uptake might influence inflammatory responses, thereby potentiating adipose tissue inflammation and insulin resistance in obesity." (PMID 34165214, 2021). "Meanwhile, NK administration notably reduced the overexpression of VLDLR in iNOS+ ATMs compared to that in the HFD group, supporting the hypothesis indicating the inhibitory role of NK in obesity and obesity‐induced inflammation." (PMID 34165214, 2021). "Although it needs to be elucidated how cellular VLDL could be converted into C16:0 ceramides in macrophages, our data suggest that macrophage VLDLR could participate in alteration of certain sphingolipids via VLDL uptaking, which eventually leads to insulin resistance in obesity." (PMID 29057873, 2017). "However, it remains largely unknown whether VLDLR-mediated VLDL uptake in macrophages is an important factor in mediating adipose tissue inflammation and insulin resistance in obesity." (PMID 29057873, 2017). "However, whether lipid uptake via VLDLR in macrophages affects obesity-induced inflammatory responses and insulin resistance is not well understood." (PMID 29057873, 2017).